MIF (macrophage migration inhibitory factor)
Diseases named in the same sentence as MIF in open-access papers (continued):
Sharing a sentence is not in itself a finding about the gene and the disease.
tumor (continued). "This was associated to lower levels of tumor-associated CD4(+)Tregs in MIF (-/-) than MIF(+/+) mice." (PMID 29707160, 2018). "At day 10 of tumor growth, the MIF-deficient tumors contain significantly more IFNgamma-producing CD8+ and CD4+ T cells." (PMID 29864117, 2018). "MIF deficiency or treatment with a MIF antagonist attenuated tumor-induced TAM polarization and reduced expression of angiogenesis-related genes in TAMs." (PMID 29618368, 2018). "Our results implicated the crucial role of MIF and its downstream pathway in providing an additional blood supply for aggressive tumor growth and adaption to a severe environment." (PMID 29113309, 2017). "Anti-MIF treatment efficiently suppresses tumor-associated angiogenesis, tumor growth, and autoimmune diseases such as human rheumatoid arthritis and cancer." (PMID 29247872, 2017). "MIF deficiency or treatment with an MIF antagonist was shown to attenuate tumor-induced TAM polarization and reduce the expression of proangiogenic genes in TAMs." (PMID 28241846, 2017). "MIF is a pleiotropic cytokine produced by many cell types that is associated with promotion of tumor growth and invasiveness through effects on both breast epithelial and immune cells." (PMID 27058619, 2017). "MIF, both excreted by tumor cells and macrophages, has been linked to tumor promotion in paracrine and autocrine manners." (PMID 28471401, 2017). "The overexpression of MIF was associated with cervical metastasis, perineural invasion, deeper tumor invasion, higher overall stage, and a poorer prognosis." (PMID 27788497, 2017). "The macrophage migration inhibitory factor (MIF) has been increasingly implicated in cancer development and progression by promoting inflammation, angiogenesis, tumor cell survival and immune suppression." (PMID 26741693, 2016). "Conversely, genes over-expressed in MIF low/Ddx6 high samples were enriched (p = 5.09E–05) for genes down-regulated in the same study, thus supporting the association of high human MIF and low mouse Ddx6 expression with tumor hypoxia." (PMID 26980748, 2016). "MIF is a pro-inflammatory mediator whose expression is closely linked to the process of oncogenic transformation and tumor growth." (PMID 26352431, 2015). "In these cancers, MIF overexpression has been associated with a concomitant increase in: a) tumor invasion/migration, b) metastasis and c) angiogenesis." (PMID 25050663, 2014). "The potential for MIF to be involved in proliferation, invasion, MET, and transformation in our study and others suggest that MIF blockade should be examined as a potential tumor target in inflammation-associated cancers." (PMID 24887129, 2014). "The mechanisms responsible for this CTL deficiency, probably include MIF-induced downregulation of receptors involved in tumor cell recognition and/or excess T cell activation, leading to cell death." (PMID 25050663, 2014). "Our results indicated that increased expression of MIF and cyclin D1 was significantly associated with tumor size." (PMID 25015194, 2014). "MIF overexpression was significantly associated with tumor size and intrahepatic metastasis, suggesting that MIF plays an important role in HCC progression." (PMID 25015194, 2014). "MIF deficiency or treatment with a MIF antagonist attenuates tumor-induced TAM polarization and reduces the expression of pro-angiogenic genes in TAMs." (PMID 24314323, 2013). "The cytokine MIF is over-expressed in tumors and is associated with tumor proliferation, angiogenesis and metastasis." (PMID 22408433, 2012). "First studies already indicate that MIF expression and MIF signalling are associated with tumor angiogenesis." (PMID 22973314, 2012). "Increased MIF mRNA expression and serum MIF levels have been associated with progression of PCa when tumor and benign tissue from matched samples were compared." (PMID 21586128, 2011). "MIF expression was highly significantly associated with tumour size (pT) in an inverse manner (p = 0.007)." (PMID 19602265, 2009).
tumor (continued). "MIF is identified as an intracellular signaling molecule and is implicated in the process of tumor progression, and also strongly enhances neovascularization." (PMID 18493321, 2008). "Following these findings, it became evident that MIF is involved in the development of lymphoma and tumor-associated angiogenesis." (PMID 18493321, 2008). "Our study compliments these findings in an in vivo model by showing a statistically significant increase in tumor associated vascular structures in MIF WT compared to KO mice." (PMID 17650334, 2007). "CD74 is also known to be a high affinity binding protein for macrophage migration-inhibitory factor (MIF) which is implicated in tumor cell growth and angiogenesis." (PMID 19662225, 2007). "Data from our previous study (using a much smaller data set) gave some indication that increased MIF mRNA was associated with more invasive, aggressive tumor." (PMID 16000172, 2005). "Trajectory analysis uncovered a specific lineage (Lineage 4) driving the normal-to-malignant transition, while cell communication analysis highlighted interactions between malignant cells and tumor-associated macrophages (TAMs) mediated by MIF and APP signaling pathways." (PMID 42089585, 2026). "Factors such as the local immune contexture, presence of specific co-receptors, and tumor mutational burden influence whether MIF acts primarily as a promoter or modulator of cancer progression." (PMID 41159021, 2025). "The MIF pathway, in particular, has been implicated in tumor inflammation and immune evasion, and its activation in NOP10+/NHP2+ PTCs may facilitate cross-talk with macrophages and T cells, contributing to an immunosuppressive niche in the ccRCC TME." (PMID 41357133, 2025). "Given that MIF has been implicated as a mediator of macrophage heterogeneity, future studies classifying macrophages in the context of MIF elimination will expand our understanding of the effects of MIF in the tumor microenvironment." (PMID 40131169, 2025). "Additionally, the study found that TNBC tumor tissues with high MIF expression exhibited a significant increase in M2-type macrophages, and high MIF expression was associated with worse clinicopathological stages and patient prognosis." (PMID 40867511, 2025). "However, once tumors were established, MIF-deficient mice lost their overall inflammatory responses and instead, exhibited reduced tumor-associated macrophage recruitment and angiogenesis." (PMID 40835826, 2025). "Additionally, MIF modulates tumor-associated macrophages (TAMs) and recruits regulatory myeloid populations, contributing to immune evasion in EBV-associated tumors." (PMID 41472252, 2025). "Furthermore, in a different study, it was found that MIF overexpression in tumor cells is substantially linked to lymph node metastases, advanced clinical stage, and a poor prognosis and so increases its potential to be prognostic biomarker." (PMID 41159021, 2025). "Like MIF, D‐DT expression is elevated across multiple tumors where it is implicated in aggressiveness, and both mediators are highly correlated at the mRNA and protein levels in the tumor and blood of cancer patients, respectively." (PMID 40131169, 2025). "We further identified that high-RiboSis-activity subpopulations drive microenvironmental immunosuppression via the MIF-(CD74+CD44) axis: CellChat analysis validated this axis promotes myeloid cell polarization toward M2-type tumor-associated macrophages while impairing T-cell activation." (PMID 41394823, 2025). "A novel insight from our single-cell RNA sequencing analysis is that ZDHHC9-overexpressing BC cells may shape the TME by engaging tumor-associated macrophages (TAMs) through the macrophage migration inhibitory factor (MIF) pathway." (PMID 40740766, 2025).
tumor (continued). "Collectively, these findings suggest that CD99- and MIF-mediated signaling may represent important components of canine immune homeostasis that may extend beyond the steady state to inflammatory or tumor-associated contexts." (PMID 41488614, 2025). "Studies have shown that in kidney renal clear cell carcinoma, the strong interactions between tumor cells and tumor-associated macrophages, driven by MIF and its receptors CD74 and CD44, are critically involved in tumor progression, angiogenesis, and the mechanism of immune evasion." (PMID 40051627, 2025). "Additionally, RNA m6A methylation-associated cellular subpopulations within the TME and tumor epithelial cells can participate in many and comprehensive interactions through ligand-receptor pairings, such as MIF-(CD74+CD44)." (PMID 40842994, 2025). "Furthermore, research has confirmed that MIF acts on T cells, causing the suppression of T cell activity and thereby mediating tumor immune escape." (PMID 40620715, 2025). "Moreover a study confirmed that tumor associated MIF suppresses T-cell activation through suppressing three mechanisms of T-cell activation: cytokine, solid-phase anti-CD3,and allogeneic MHC." (PMID 41159021, 2025). "MIF secreted by stromal cells could bind CD74 on tumor epithelial cells, and MIF-deficient stromal cells are known to exhibit reduced functionality." (PMID 40835826, 2025). "MIF is well‐known for its involvement in various biological processes including inflammation, immune regulation, cell proliferation and survival, with potential to be associated with tumour immune evasion and tumour progression." (PMID 39602465, 2024). "An MIF antagonist attenuates tumor-associated macrophage polarization toward the M2 phenotype." (PMID 39202723, 2024). "For instance, targeting MIF signaling could sensitize chemotherapy, as MIF has been found to cause temozolomide resistance by activating the tumor intrinsic PI3K/AKT signaling pathway." (PMID 38515213, 2024). "We hypothesized that radiation could improve hypoxia in the microenvironment of NSCLC brain metastases, downregulate HIF-1α expression, and cause a decrease in MIF release from tumor cells." (PMID 38685050, 2024). "In addition, loss of STING also limited the OSU13-mediated induction of MIF that suppresses antiinflammatory effects of glucocorticoids, which play pivotal role in tumor immune evasion." (PMID 38900577, 2024). "Importantly, MIF is known to promote tumor-associated immune cell evasion by inhibiting DC migration, maturation, and antigen presentation, which helps the development of anti-tumor CD4+ and CD8+ effector T cells." (PMID 38730725, 2024). "Further studies show HIF-1α stabilization in hypoxic conditions may concurrently activate MIF and upregulate PD-L1 expression, conferring tumor survival in oxygen-deficient intratumoral environments." (PMID 38732068, 2024). "A crucial role of MIF in promoting tumor growth was demonstrated in MIF-deficient mice." (PMID 38548753, 2024). "Our research indicates that PLOD2 + SAA1 + tumor cells might be capable of communicating with tumor-associated macrophages (TAMs) through specific ligand-receptor pairs, such as MIF-(CD74 + CXCR4), MDK-LRP1 and C3-C3AR1." (PMID 38951896, 2024). "NB cells signal to myeloid cells through MK and MIF pathways and promote an inflammatory environment, conveying a tumor-associated monocyte phenotype that is attributed to the rewiring of key signaling/transcription factor modules of myeloid lineage commitment and monocyte polarization." (PMID 37365178, 2023). "Similarly, MIF has been implicated in governing both inflammatory and tumor promoting functions in tumor-associated macrophages." (PMID 37365178, 2023). "Furthermore, tumor infiltration and immunosuppression by MDSCs, which are dependent on tumor cell expression of macrophage migration inhibitory factor (MIF), have been directly associated with poor prognosis." (PMID 36768342, 2023).
tumor (continued). "Interestingly, it has been reported that MIF can shape the heterogeneity of macrophages, which can induce pro-tumorigenic polarization of tumor-associated macrophages." (PMID 37483625, 2023). "Results showed that the selected AGs in our risk model (BAK1, DKK1, and MIF) were negatively related to the infiltration levels of tumor-infiltrating lymphocytes (including T cells, B cells, and macrophages), suggesting a low immunosuppressive activity for HNSCC patients of the high-risk groups." (PMID 35619896, 2022). "Interestingly, we also identified high expression of MIF in BM-derived disseminated NB tumor cells, and thus associated with NB infiltration." (PMID 35715791, 2022). "Mechanistically, MIF-pathway overactivation is likely a manifestation of either the macrophage aggregation caused by Helicobacter pylori infection or accumulations of tumor-associated macrophages, which further predisposes epithelial cells to malignant transformation." (PMID 36046240, 2022). "Indeed, macrophages specifically infiltrated tumors, suggesting that MIF regulates the chemotaxis of tumor-associated macrophages to promote CRC tumorigenesis." (PMID 33542244, 2021). "Furthermore, MIF has been implicated in the progression of vascular mimicry, in which tumour cells organise in vascular-like structures to receive sufficient blood supply." (PMID 33803414, 2021). "Moreover, at 12 weeks post-AOM, during which the CRC tumors are well established, MIF deficiency decreased tumor burden and numbers." (PMID 33542244, 2021). "Furthermore, the macrophage migration inhibitory factor MIF has been associated with tumor aggressiveness and metastatic spread." (PMID 33273682, 2021). "MIF affects both tumor progression and tumor-associated immune responses." (PMID 34407796, 2021). "Higher MIF expression in tumor tissue was associated with worse survival of PDAC patients." (PMID 33776775, 2021). "High expression of MIF is associated with tumor aggressiveness and poor patient outcomes." (PMID 34485124, 2021). "Mif deletion protects mice from inflammation-associated tumor initiation, confirming the action of MIF on host inflammatory pathways; however, macrophage recruitment, neoangiogenesis, and proliferative responses are reduced in Mif-deficient tumors once the tumors are established." (PMID 33542244, 2021). "Combined, these findings suggest that MIF promotes tumor-associated immune evasion by inhibiting DC infiltration, maturation, and antigen presentation; all of which are inherently required for the development of anti-tumor CD4+ and CD8+ T cell effector functions." (PMID 33324425, 2020). "Because each of these cell types influences the initiation, growth, progression, and/or metastatic dissemination of tumors, we will attempt to summarize how MIF shapes tumor-associated immune responses focusing on individual cell effectors and their relative contributions to pro/anti-tumor immunity." (PMID 33324425, 2020). "In addition, key enzymes such as amylases (Amy2a5) which show ablated gene expression in MIF-deficient mice are reported to be up-regulated in tumor-associated MDSCs." (PMID 31708913, 2019). "Importantly, compared to the WT intestinal epithelium, lower percentages of tumor-associated Møs were found in the MIF−/− intestinal epithelium." (PMID 31360118, 2019). "Indeed, it has been shown that MIF promotes macrophage angiogenic potential by acting on tumor-associated macrophage (TAM) polarization in lung metastases." (PMID 31013837, 2019). "Next, immunohistochemical analysis was used to reveal whether MIF, an inflammatory and angiogenic molecule associated with tumor pathology, is also expressed in the context of PDR." (PMID 31866994, 2019). "The increased tumor development in MIF-deficient mice was also reflected in the tumor burden." (PMID 31360118, 2019).
tumor (continued). "Multiple cytokines, including tumor necrosis factor (TNF)-α, interleukin (IL)-6, IL-17, IL-12, IL-23, IL-10, transforming growth factor (TGF)-β, and macrophage migration inhibitory factor, have been associated with human cancers and can promote or inhibit tumor development." (PMID 31043452, 2019). "This suggests that the observed increase in IFNgamma-producing T cells in the tumor microenvironment may explain the decreased growth of the MIF-deficient tumors in immune competent animals." (PMID 29864117, 2018). "Nonetheless, the role of MIF as angiogenetic factor in GBM has recently been questioned by the evidence that bevacizumab resistance in GBM is driven by reduced MIF at the tumor edge causing proliferative expansion of M2 macrophages, which in turn promotes tumor growth." (PMID 29707160, 2018). "In order to more closely mimic the more nutrient-deficient microenvironment murine tumor cells might experience upon orthotopic implant into the mammary fat pad, WT or MIF KD 4T1 cells were cultured in vitro in 1% serum or serum-free media." (PMID 29864117, 2018). "Accumulated evidence has proved that MIF was associated with tumor angiogenesis." (PMID 27788497, 2017). "This pro-stimulatory effect could also be due, in situ, to MIF secreted by cells from the tumor microenvironment, such as tumor-associated macrophages, tumor-infiltrating lymphocytes, or cancer-associated fibroblasts." (PMID 26883190, 2016). "Such a decrease of MIF activity was associated with inhibition of tumor angiogenesis." (PMID 26883190, 2016). "Higher MIF expression was significantly associated with a higher pT status, a higher pN status, a higher overall pathological stage, positive perineural invasion, and greater tumor depth (P < 0.001 for all)." (PMID 26138061, 2015). "Finally, host macrophage-produced MIF was shown to polarize tumor-associated macrophages (TAMs) towards an immunosuppressive M2 phenotype, whereas MIF inhibition or gene loss (MIF−/−) reversed TAM functionalities to M1-type." (PMID 25050663, 2014). "However, several studies evaluating tumor initiation and maintenance in MIF-deficient settings reveal only modest decreases in tumor burden." (PMID 24932684, 2014). "Increased MIF positivity in cancer and stromal cells, including tumor-associated macrophages, correlated inversely with nodal involvement and also led to suggestions for a role of MIF in tumor-stroma interactions." (PMID 24939415, 2014). "This is consistent with the hypothesis that MIF could modulate the tumor size by inhibiting recruitment of cancer-associated fibroblasts (CAFs)/myofibroblasts, eventually resulting in retardation of tumor growth." (PMID 24939415, 2014). "Additionally, MIF involvement in highly dynamic vasoproliferative events, such as tumor-associated angiogenesis, qualifies this immune regulator as a conventional marker for luteal angiogenesis." (PMID 25125800, 2014). "Hypoxia, a hallmark feature of tumors, increases MIF expression from tumor cells." (PMID 22408433, 2012). "Autocrine MIF activation loops have been implicated in tumour cell growth." (PMID 19602265, 2009). "Thus large tumours (>2 cm) being associated with poor prognosis predominantly expressed low levels of MIF (IRS<4)." (PMID 19602265, 2009). "In addition to MIF's potent effects on the immune system, MIF is linked to fundamental processes conferring cell proliferation, cell survival, angiogenesis, and tumor invasiveness." (PMID 18493321, 2008). "Tumor presence was associated with nuclear redistribution of MIF." (PMID 17650334, 2007).